MITF (melanocyte inducing transcription factor)
Diseases named in the same sentence as MITF in open-access papers (continued):
Sharing a sentence is not in itself a finding about the gene and the disease.
melanoma (continued). "As mentioned already, MITF is considered to be the “master gene” of melanocyte differentiation and has an essential role in the proliferation, survival, senescence, migration, invasion, DNA repair, and metabolism of melanoma cells." (PMID 35158973, 2022). "What's more, LOXL3 could also regulate the metastasis of melanoma via affecting the expression of MITF, TWIST1, SNAIL1 and PRRX1, which were molecules that involved in EMT process." (PMID 36324258, 2022). "Moreover, the depletion of MITF attenuated the response to induced autophagy, and decreased melanoma immunogenicity and the response to immunotherapy." (PMID 35055021, 2022). "Indeed, BRN2 directly inactivates MITF transcription by binding to its promoter in 501-mel melanoma cells ectopically expressing Brn-2, whereas high levels of MITF allow the transcription of miR-211, which impairs BRN2 translation." (PMID 36551603, 2022). "Following a period of tumour growth, we transferred fish to a higher temperature to turn off MITF activity and cause tumour regression until no melanoma was detectable morphologically (5-10 weeks)." (PMID 35929478, 2022). "Transcript levels of conventional melanocytic markers (e.g. SILV, MLANA, and TYR) which are known to be dominantly regulated by MITF4,51, and of MITF itself were significantly inversely correlated with DNA methylation in the cell lines and TCGA melanoma samples." (PMID 35810190, 2022). "Both MITF and CDK2 could influence the expression of a number of genes associated with melanoma invasion, whilst being dynamically regulated by other genes within the melanoma cell." (PMID 36776379, 2022). "Interestingly, MITF activity has been recently shown to be regulated by a direct interaction with RAF proteins in melanoma cells." (PMID 35682684, 2022). "The upregulation of phosphorylated CREB and MITF indicates polymyxin B could induce melanogenesis in SK-MEL-2 melanoma cells by activating CREB followed by MITF and its downstream melanogenic genes." (PMID 35377227, 2022). "MITF is the major regulator of the plasticity of the melanoma cell phenotype." (PMID 35565444, 2022). "Thus, independently of the activating lesion, melanoma cells with mutationally active MAPK and a functional MITF pathway are vulnerable to DUSP4 depletion." (PMID 35580987, 2022). "Other melanoma-related genetic alterations consist of polymorphisms in genes coding for: melanocortin 1 receptor (MC1R) and melanocyte inducing transcription factor (MITF), also known as microphthalmia-associated transcription factor." (PMID 35158770, 2022). "Thus, the response of PGC1α to MITF is the main regulatory factor of mitochondrial respiration in melanoma." (PMID 36620597, 2022). "Melanoma cells in which the TR1 gene (TXNRD1) was disrupted using Crispr/Cas9 showed more dramatic effects including the complete loss of the melanocyte-specific isoform of MITF; other MITF isoforms were unaffected." (PMID 36291795, 2022). "Therefore, inhibition of MITF–PGC1a axis and mitochondrial function is a potential therapeutic strategy to avert melanoma development and boost the efficacy of MAPK inhibition." (PMID 36224606, 2022). "Furthermore, the expression of EGFR and MITF are inversely correlated in melanoma and forced expression of MITF in melanoma and colon cancer cells inhibits EGFR expression." (PMID 35406721, 2022). "In MITF-positive metastatic melanoma cell lines, SKMEL28 and MNT1, the observed differences might arise from cell metastasis-initiating capacity." (PMID 36776379, 2022). "However, when injecting such cells in NSG mice, we observed that the undifferentiated SOX10– melanoma cells developed significantly smaller tumors compared with SOX10+MITF– melanoma cells." (PMID 36040798, 2022).
melanoma (continued). "Upregulation of GPR143 in chemoresistant melanoma may thus be due to upregulation of MITF, since MITF directly controls GPR143 expression." (PMID 35495622, 2022). "Effects of CRISPR/Cas9-mediated SOX10 knockout in MITF-methylated melanoma cells." (PMID 36040798, 2022). "MITF is thought to be the very determinant of melanoma cell plasticity." (PMID 35682684, 2022). "In addition, The Cancer Genome Atlas (TCGA) analysis has identified three transcriptomic subclasses of melanomas with distinct survival rates, one of them being defined by low MITF expression." (PMID 35798875, 2022). "To test this hypothesis, we silenced MITF expression in mutant melanoma cells and evaluated cell growth over time." (PMID 35580987, 2022). "Depletion of SOX10 in MITF-methylated melanoma cells using CRISPR/Cas9 supported these findings." (PMID 36040798, 2022). "Using uniform manifold approximation and projection (UMAP) analysis on 1,500 genes with largest expression variation across the melanoma cell lines, we found that MITF and other melanocyte lineage genes contributed significantly to the main separation of melanoma cell lines." (PMID 36040798, 2022). "Interestingly, a knock-down of MITF in B16F10 melanoma cells and overexpression of MITF in YUMM1.1 cells led to increased tumor growth in vivo in mice." (PMID 35159049, 2022). "Additionally, HDAC inhibitors have been previously shown to inhibit the expression of MITF, and combined with nivolumab in the treatment of advanced melanoma it achieved good ORR, and related clinical trials are under recruitment (NCT04674683)." (PMID 36125617, 2022). "Notably, a MITFlow zebrafish model has been established to address a subgroup of melanoma patients with low MITF having a poor prognosis." (PMID 35740696, 2022). "Decreased expression of MITF was reported to promote the migration ability of melanoma cells." (PMID 36612077, 2022). "In addition, long-term TGFβ exposure can induce a dedifferentiated EMT-like state with the melanoma invasive phenotype characterized by MITF downregulation and mesenchymal marker upregulation, thus driving the invasiveness of the melanoma." (PMID 35565234, 2022). "In a study on xenograft models to stimulate awakening in dormant cells, thus making them more susceptible to treatment, methotrexate was reported to favor the phenotypic switch from a MITF low to an MITF high state, thus sensitizing melanoma cells to a tyrosinase-processed antifolate prodrug." (PMID 35565234, 2022). "This would potentially include MITF, a key regulator of melanocyte and melanoma biology, or USF1/2." (PMID 34819350, 2021). "Importantly, we found that in the zebrafish data the ECM signature was specifically induced in the single cell cluster from MITF-low superficial tumors (representing minimal residual disease) compared to other single-cell clusters from MITF-high melanomas." (PMID 33438577, 2021). "Recent evidence also indicates that MITF can impact the anti-melanoma immune responses." (PMID 34573422, 2021). "Thus, permanently losing MITF reprograms gene expression toward the drug-resistant state, suggesting that MITF-KO cells can be a tool to study drug resistance in melanoma." (PMID 33438577, 2021). "Four known melanoma cell marker genes, MITF, MLANA, PMEL and TYR, were obtained from CellMarker." (PMID 34784909, 2021). "Furthermore the role of MITF in the regulation of the BCL2 gene activity has already been studied in melanoma cells." (PMID 34289891, 2021). "MITF is sensitive and specific in identifying melanoma cells." (PMID 34441278, 2021). "Both MITF and LEF1 have been implicated in melanoma survival and resistance." (PMID 33647315, 2021). "Additionally, further work is needed to define more clearly the role of MITF-low-expressing states in primary or adaptive resistance to immune checkpoint blockade in melanoma." (PMID 34771465, 2021).
melanoma (continued). "This may alter both the plasticity of melanoma cells under stress (via MITF) and their ability to produce new and functional mitochondria (via PGC1α)." (PMID 33806766, 2021). "MLANA/MART1 was reported to be transcriptionally regulated by MITF in melanocytes and melanomas." (PMID 34722301, 2021). "To investigate the palbociclib-driven changes in mitochondrial metabolism, we examined mRNA expression or protein levels of key regulators of mitochondrial biogenesis in melanoma (MITF, PGC1α and TFAM) as well as protein levels of key components of the five mitochondrial OXPHOS complexes." (PMID 33572972, 2021). "Furthermore, MITF is also a key determinant of melanoma cell plasticity and tumor heterogeneity in the tumor microenvironment, which are considered among major obstacles for effective immunotherapy." (PMID 35008245, 2021). "Melanoma cells may also acquire resistance to MAPK inhibitors through a mechanism dependent on elevated expression of MITF." (PMID 33800547, 2021). "Most of all, much of the pathophysiology of melanoma is driven by the activity of MITF." (PMID 33803640, 2021). "We tested whether melanoma tumors in TCGA that have high MITF expression also express important EMT regulators." (PMID 33438577, 2021). "It is tempting to speculate that a reciprocal regulation of BRN2 and MITF expression enables a swift switch between proliferative and invasive phenotypes, which is ultimately required for seeding and outgrowth of melanoma cells at secondary metastatic sites." (PMID 34604096, 2021). "Interestingly, it was recently shown that TGFA belongs to the genes most strongly upregulated in SK-MEL-28 MITF-knockout melanoma cells compared to their controls." (PMID 33916908, 2021). "Next, we investigated whether the inhibitory effect on melanoma migration and invasion following HuR-NP treatment could partly be due to MITF." (PMID 33418925, 2021). "The drastic differences between these two studies may be due to the amelanotic versus highly pigmented nature of the used melanoma lines, the status of the B-RAF mutation, MITF or other upstream pathways controlling MITF." (PMID 34356645, 2021). "In addition, it reduces phosphorylation of Akt, mTOR, microphthalmia-associated transcription factor (MITF), and p70S6K proteins in human melanoma 451Lu cells in a dose-dependent manner." (PMID 34830339, 2021). "Interestingly, we observed increased expression of TGFß1, encoding an important regulator of ECM-related genes, in the MITF-KO cells and MITFlow melanoma tumors." (PMID 33438577, 2021). "The molecular pathways activated by EMT-TFs and MITF, during the melanocyte differentiation program, may be reactivated during melanomagenesis, which explains melanoma heterogeneity and plasticity." (PMID 34830940, 2021). "Actually, the phenotypic states of melanoma cells are not limited to an MITF-positive/drug sensitive ‘proliferative’ and an MITF-low/drug resilient ‘invasive’ cell state; however, to date, a revised MITF rheostat model, including six different phenotypic states, has been reported." (PMID 34830940, 2021). "It was described that Ubc9 targets the MITF to the proteasome for degradation, and may favor the transition toward a dedifferentiated and metastatic melanoma phenotype." (PMID 33800394, 2021). "Finally, immunostaining of a panel of human melanoma cell lines showed robust expression of MITF and HuR, albeit at varying levels for the two proteins in the cell lines." (PMID 33418925, 2021). "We then hypothesized that an intrinsic melanoma cell state indicated by MITF mRNA levels and CD8+ T cell infiltration in combination is essential for predicting clinical response." (PMID 34210820, 2021). "Knocking down β-catenin in melanoma cells also reduced MITF mRNA by 2.8-fold." (PMID 33647315, 2021). "Collectively, the results indicate that the presence of MITF could differentially modulate the response of the immune system toward irradiated melanoma cells." (PMID 33789714, 2021).
melanoma (continued). "Besides the MAPK pathway, MITF is very important for melanoma progression as it controls melanocyte-specific proliferation." (PMID 34944799, 2021). "Melanocytes and melanoma cells were labelled with pigment cell specific anti-MiTF antibodies." (PMID 34616669, 2021). "However, antibody staining suggests that cells lacking MITF are abundant in melanomas and single-cell sequencing of human xenotransplants and of zebrafish melanoma models suggest the existence of cells with very low MITF expression." (PMID 33438577, 2021). "MITF plays a role in multiple activity levels that determine the fate of melanoma cells." (PMID 34784909, 2021). "The role of Wnt/β-catenin/MITF pathway in melanoma cell proliferation is well established." (PMID 33647315, 2021). "Furthermore, inhibiting HuR offered the additional advantage of reducing MITF expression in melanoma cells, and combinatorial therapy targeting HuR and MEK1/2 produced synergistic antitumor activity." (PMID 33418925, 2021). "MITF was initially described to control differentiation and pigmentation through the regulation of genes involved in melanogenesis, then MITF was also involved in melanoma cell survival and proliferation, while it represses motility and invasive capacities." (PMID 33462405, 2021). "Consequently, while melanoma MITFLow cells can be effectively suppressed by NK-mediated killing, MITF-expressing cells escape NK cell surveillance." (PMID 33789714, 2021). "Wnt signalling is known to stabilize MITF protein levels in melanoma cells." (PMID 33875769, 2021). "MITF in conjunction with mutant BRAF(V600E), an activating mutation commonly present in melanocytic lesions, trigger transformation of immortalized melanocytes, functioning as a melanoma oncogene." (PMID 34289891, 2021). "HDAC10 restores melanogenesis by deacetylating paired box protein 3 (Pax3) and KRAB-associated protein 1 (KAP1), which relieves the repressed promoters of microphthalmia-associated transcription factor (MITF) as well as tyrosinase-related protein 1 (TRP-1) and TRP-2 in melanoma cells." (PMID 33997894, 2021). "Additionally, combinatorial therapy incorporating MEK inhibitor holds promise in overriding MITF-mediated drug resistance in melanoma." (PMID 33418925, 2021). "Also, overexpression of miR-182 promotes metastasis and survival of melanoma cells in vitro by transcriptionally suppressing FoxO3a and the melanocyte inducing transcription factor (MITF)." (PMID 34418600, 2021). "First, MITF is a downstream target of numerous signaling pathways and is subject to diverse post-translational modifications, which can direct MITF to different sets of target genes that regulate different functions in melanoma, dependent on physiological context." (PMID 34356645, 2021). "Accordingly, in melanoma cells that constitutionally overexpress MiTF, its siRNA-mediated depletion leads to FANC protein downregulation and the entry of melanoma cells into senescence, at which point they accumulate chromosomal damage and mitotic abnormalities." (PMID 33441180, 2021). "Interestingly, regional lymph node metastases showed positive S100 protein, MITF, and tyrosinase staining, further emphasizing the protean nature of melanoma." (PMID 34449584, 2021). "STAT3 was shown to repress MITF and reduces the proliferation of melanoma cells." (PMID 34638912, 2021). "As a first step in assessing the potential impact of MITF on the anti-melanoma immune response, we developed an immunogenic B16/F10 melanoma model that accurately reflects the human disease by subjecting cells to irradiation prior to inoculation into immunocompetent mice." (PMID 33789714, 2021).
melanoma (continued). "Indeed, GLI2 was found to play a major role in suppressing MITF expression in human melanoma specimens, and the expression of GLI1/2 was correlated with EGFR/AXL signatures." (PMID 34572373, 2021). "A comprehensive study of The Cancer Genome Atlas (TCGA) Skin and Cutaneous Melanoma (SKCM) dataset (hereafter referred to as “TCGA melanoma”) defined three transcriptomic subsets of melanoma (‘keratin’, ‘MITF-low’ and ‘immune’), each with a distinct microRNA expression profile." (PMID 34771465, 2021). "In melanoma, one of the major determinants of phenotypic identity is the lineage survival oncogene MITF that integrates diverse microenvironmental cues to coordinate melanoma survival, senescence bypass, differentiation, proliferation, invasion, metabolism and DNA damage repair." (PMID 33789714, 2021). "Further studies to investigate the interplay of these factors and pathways with the master regulator MITF may facilitate the development of new therapies to overcome drug resistance problems in melanoma." (PMID 33840166, 2021). "Interestingly, MITF was negatively correlated with AXL post TNFα in the dedifferentiated melanoma subtype." (PMID 34073253, 2021). "Due to its central role in melanogenesis, MITF in melanoma has been extensively studied so far." (PMID 34071193, 2021). "A role for MITF as a repressor has been described in both melanoma cells and immune cells." (PMID 33438577, 2021). "Our data showed that the number of paxillin-positive dots was induced in both MITF-KO and miR-MITF cells as compared to controls (g h) and paxillin expression was inversely correlated with MITF expression in melanoma tissues and cell lines." (PMID 33438577, 2021). "Since melanoma cells can mediate these effects on their own, in the absence of the tumor microenvironment, this suggests that this process is cell-autonomous and under the direction of MITF which instructs the cells to create their own microenvironment." (PMID 33438577, 2021). "Moreover, Western blot analysis showed that the protein expression levels of MITF in B16 melanoma cells transfected with the miR-7013-3p mimic were lower than those in cells transfected with the mimic NC." (PMID 33746605, 2021). "Moreover, when the levels of both BRN2 and MITF are reduced in human melanoma cell lines, the level of AXL mRNA is induced." (PMID 34140478, 2021). "Next, we analyzed whether the collagens that were differentially expressed in the MITF-KD or KO melanoma cell lines were also affected by MITF in melanoma tumors in TCGA." (PMID 33438577, 2021). "MITF activity increases the expression of Rab27A, a small GTPase that controls the docking of MVBs to the PM, suggesting a role for MITF in release of melanoma exosomes." (PMID 33321449, 2021). "In the most comprehensive study at present, analyzing gene expression and genetic patterns of melanoma samples using RNA-seq technology, three major tumor subtypes were identified, termed “immune”, “keratin”, and “MITF-low”, standing for activated functional gene signatures in these samples." (PMID 34281234, 2021). "To determine whether Olig2 regulates MITF expression, we inhibited Olig2 in two melanoma cells and then identified the protein expression of MITF by immunoblotting." (PMID 33833342, 2021). "Additionally, the methylation patterns of the MITF promoter can change during melanoma progression, and it can be reactivated in melanoma by hypomethylation." (PMID 34944799, 2021). "In this context, inhibiting ADAM10 activity, but maintaining MITF transcriptional function could represents a rational strategy to guide melanoma cells to their destruction by the immune system." (PMID 33789714, 2021).